ADAMTS1 (ADAM metallopeptidase with thrombospondin type 1 motif 1)
Description:
Metalloprotease which cleaves aggrecan, a cartilage proteoglycan, at the '1938-Glu-|-Leu-1939' site (within the chondroitin sulfate attachment domain), and may be involved in its turnover (By similarity). Also cleaves COMP. Has angiogenic inhibitor activity. May play a critical role in follicular rupture (By similarity).
Synonyms: KIAA1346; METH1; C3-C5
Tractability: Small molecule: a structure with a bound ligand is known; a high-quality ligand is known; it has a binding pocket of medium quality; it belongs to a druggable protein family. Antibody: UniProt places it where antibodies can reach, with medium confidence; UniProt predicts a signal peptide or a membrane-spanning region; its Gene Ontology location is reachable by antibodies, with medium confidence. PROTAC: ubiquitination databases record sites on it; a small molecule that binds it is known.
Target class: Metallo protease MAM clan; Metallo protease; Protease; Enzyme; Metallo protease M12B subfamily
Gene: Protein-coding gene on chromosome 21 (26,835,755 to 26,845,409, reverse strand). Ensembl gene ENSG00000154734.
Subcellular location: Secreted, extracellular space, extracellular matrix
Subcellular location (Human Protein Atlas): Plasma membrane; Predicted to be secreted
Pathways (Reactome):
Disease: Defective B3GALTL causes PpS
Extracellular matrix organization: Degradation of the extracellular matrix
Metabolism of proteins: O-glycosylation of TSR domain-containing proteins
Gene Ontology:
Molecular function: metalloendopeptidase activity; protein binding; metallopeptidase activity; heparin binding; zinc ion binding
Biological process: negative regulation of angiogenesis; positive regulation of G1/S transition of mitotic cell cycle; positive regulation of vascular associated smooth muscle cell migration; positive regulation of vascular associated smooth muscle cell proliferation; extracellular matrix organization; integrin-mediated signaling pathway; negative regulation of cell population proliferation; proteolysis
Cellular component: extracellular matrix; basement membrane; cytoplasmic vesicle
Genetic constraint (gnomAD): Loss-of-function variants: 19 observed, 84.67 expected, observed/expected ratio (o/e) 0.22, 90% interval 0.16 to 0.33. The upper end of that interval is the gene's LOEUF score, 0.33, which puts it in group 1 of 6, group 1 being the genes least tolerant of losing a copy. Missense variants: 1,240 observed, 1,252 expected, observed/expected ratio (o/e) 0.99, 90% interval 0.94 to 1.04. Synonymous variants: 542 observed, 490.67 expected, observed/expected ratio (o/e) 1.1, 90% interval 1.03 to 1.19.
Homologues: Orthologues: chimpanzee ADAMTS1 (99% identical), macaque ADAMTS1 (99% identical), pig ADAMTS1 (86% identical), guinea pig ADAMTS1 (85% identical), dog ADAMTS1 (83% identical), rat Adamts1 (82% identical), mouse Adamts1 (82% identical), rabbit ADAMTS1 (80% identical), tropical clawed frog adamts1 (69% identical), zebrafish adamts1 (55% identical). Paralogues in human: ADAMTS15 (48% identical), ADAMTS8 (44% identical), ADAMTS4 (41% identical), ADAMTS9 (39% identical), ADAMTS5 (39% identical), ADAMTS20 (38% identical), ADAMTS7 (32% identical), ADAMTS12 (32% identical), ADAMTS16 (31% identical), ADAMTS6 (30% identical), ADAMTS18 (30% identical), ADAMTS17 (29% identical), and 13 more.
Diseases named in the same sentence as ADAMTS1 in open-access papers:
ADAMTS1 is named in the same sentence as 166 diseases in open-access papers, as found by Europe PMC text mining. Sharing a sentence is not in itself a finding about the gene and the disease. The quoted sentences say what the papers report.
breast carcinoma (53 papers, 2010 to 2025). "The loss of MXRA8 also led to a decrease in the expression of genes associated with breast cancer, including ADAMTS1, TIE1, and BMP2." (PMID 37762032, 2023). "In a recent study, the interaction between fibulin-1 and ADAMTS-1 was associated with antitumor effects in breast cancer cell lines." (PMID 31508361, 2019). "Here, we examined the association between TSP-1 and ADAMTS1 and the activity of ligand-activated PPARδ in terms of migration and invasion of human breast cancer cells." (PMID 29212212, 2017). "Our findings provide a new insight into the molecular mechanism underlying the regulation of ADAMTS1 in breast cancer through the Cn/NFAT pathway." (PMID 25719243, 2015). "Elevated MMP-1 and ADAMTS1 expression is associated with increased risk of bone metastasis in breast cancer patients." (PMID 23696795, 2013). "On the other hand, breast cancer cells induce ADAMTS1 secretion from cancer associated fibroblasts when co-cultured together, resulting in cancer cell invasion." (PMID 24213506, 2012). "Furthermore, increased MMP-1 and ADAMTS-1 expressions are associated with an increased risk of bone metastasis in breast cancer patients." (PMID 36338393, 2022). "Also, breast cancer cells have been shown to force normal tissue-associated fibroblasts to permanently produce the invasion-promoting protease ADAMTS1 (a disintegrin and metalloproteinase with thrombospondin motifs 1)." (PMID 29774124, 2018). "NFAT1 could bind to the promoter region of ADAMTS1 gene, which encodes a protease required for growth and metastasis of breast cancer cells." (PMID 28927426, 2017). "Previously, ADAMTS1 was reported to promote metastasis of murine breast cancer through activating EGFR by shedding HB-EGF and amphiregulin." (PMID 38263290, 2024). "Apart from extracellular ADAMTS1, the presence of ADAMTS1 in nuclei of breast cancer cells was reported." (PMID 39333870, 2024). "In breast cancer, overexpression of ADAMTS1 was shown to promote tumor progression and to be upregulated in metastatic TNBC (reviewed in40)." (PMID 37389973, 2023). "It has also been reported that overexpression of ADAMTS1 promotes pulmonary metastasis of TA3 mammary carcinoma and Lewis lung carcinoma cells." (PMID 36947712, 2023). "In transgenic MMTV-PyMT mice, whole-body ADAMTS1 knockout reduced mammary tumor size and lung metastatic burden." (PMID 37762032, 2023). "MMP-1 combined with ADAMTS1 can activate osteoclast differentiation by modulating the bone microenvironment in favor of osteoclastogenesis, to promote breast cancer bone metastasis." (PMID 35359350, 2022). "There is increasingly abundant evidence that the metalloprotease ADAMTS1 is strongly correlated with metastasis of breast cancer." (PMID 35625488, 2022). "Our previous work also showed ADAMTS-1 in breast cancer cells with different processing status, and indirect immunofluorescence detected ADAMTS-1 expression in AME cells." (PMID 36338393, 2022). "On the contrary, ADAMTS1 is an additional tumor suppressed protein, which was markedly decreased in lung, ovarian, and breast cancer." (PMID 36232317, 2022). "This is certainly the case for MMP19, involved in the development of T cells in mice; MMP11, related to several cytokines in breast cancer cells; and ADAMTS1, a known regulator of the inflammatory response." (PMID 35903133, 2022). "This was accompanied by decreased histone 3 K27 methylation at the ADAMTS1 promoter, a change that persisted even after removal of the breast cancer cells." (PMID 29774124, 2018). "Taken together, these results demonstrate that PPARδ suppresses migration and invasion of breast cancer cells by downregulating TSP-1 in a process mediated by upregulation of ADAMTS1." (PMID 29212212, 2017). "Previous research has described the differential expression of ADAMTS1 in breast cancer and a deregulation of ADAMTS1 in this cancer type." (PMID 28173833, 2017).
breast carcinoma (continued). "In particular, ADAMTS1 expression correlates positively with migration and invasion of human breast cancer MDA-MB-231 cells." (PMID 29212212, 2017). "hATT-CMs increase versican, CD44, ADAMTS1 and Adipo R1 expression in breast cancer epithelial cells." (PMID 28173833, 2017). "PPARδ-induced upregulation of ADAMTS1 is a key event during PPARδ-dependent suppression in the migration and invasion of human breast cancers MDA-MB-231, MDA-MB-435, and ZR-75-1 cells." (PMID 29212212, 2017). "Our group observed variable levels of ADAMTS-1 mRNA expression but lower levels of ADAMTS-1 protein expression in human breast cancers as compared to normal tissue, with a striking decrease observed in high-malignancy (triple-negative cases)." (PMID 27764205, 2016). "More recently, the use of a tumor-prone model for mouse mammary carcinoma reported the requirement of Adamts1 gene for invasion and progression." (PMID 27120788, 2016). "Several reports have revealed that the expression of ADAMTS1 was elevated in endometrial adenocarcinoma and breast cancer." (PMID 25936341, 2015). "Several studies have also demonstrated that ADAMTS1 is downregulated in breast cancer, prostate cancer, lung cancer, pancreatic cancer and colorectal cancer." (PMID 25936341, 2015). "In particular, we report that expression of the protease A Disintegrin And Metalloproteinase with ThromboSpondin motifs 1 (ADAMTS1), which was previously shown to be essential to mammary tumor development and metastasis, is likely a direct target of NFAT1." (PMID 25719243, 2015). "Our series of experiments further suggest that VEGF is involved in these effects of ADAMTS-1 in breast cancer cells." (PMID 23289900, 2013). "Altered ADAMTS-1 expression has been reported in different types of tumors, including breast cancer." (PMID 23289900, 2013). "For example, expression of human ADAMTS1 was shown to exert an anti-tumor effect on T47D breast cancer cells." (PMID 24213506, 2012). "In this communication, we show that, in addition to producing HGF for cancer cell growth, NAFs co-cultured with breast cancer cells also secreted ADAMTS1 for cancer cell invasion." (PMID 22514714, 2012). "Given that cancer-associated fibroblasts secrete ADAMTS1 for cancer cell invasion, it's likely that the expression of ADAMTS1 in CAFs is physiologically relevant to breast cancer progression." (PMID 22514714, 2012). "Further comparative analysis of total 10 pairs of CAF/NAF from breast cancer patients revealed that the expression of ADAMTS1 in CAFs was relatively higher than in NAF." (PMID 22514714, 2012). "It should be noted that the induced expression of ADAMTS1 indeed was observed in NAF after 4 consecutive co-incubations with breast cancer cells and the following removal of breast cancer cells for 3 passages (ex, 200N.E4.P3)." (PMID 22514714, 2012). "Next, the potential mechanism involved in the sustained expression of ADAMTS1 in NAFs after removal of the co-cultured breast cancer cells was explored." (PMID 22514714, 2012). "To test this possibility, we analyzed ADAMTS1 mRNA of CAFs from 49 breast cancer patients and found that the higher expression of ADAMTS1 mRNA of CAFs in patients was significantly correlated with lymph node metastasis." (PMID 22514714, 2012). "We further show that the level of the CAF-secreted ADAMTS1 significantly correlates with lymph node metastasis of breast cancer patients." (PMID 22514714, 2012). "How ADAMTS1 expression is induced following co-culture with breast cancer cells remains to be resolved." (PMID 22514714, 2012). "For example, ADAMTS-1 mRNA levels have been shown to be either increased or decreased in breast carcinomas." (PMID 21494557, 2011). "In a bone metastasis model of breast cancer, bone-metastatic variants of the MDA-MB-231 breast cancer cell line were found to overexpress two metalloproteinases, MMP1 and ADAMTS1." (PMID 20010942, 2010).
breast carcinoma (continued). "While an early study found that ADAMTS1 was one of several ADAMTS genes downregulated in breast cancer compared to non-neoplastic breast tissue, more recent studies have associated high ADAMTS1 expression with increased breast cancer metastasis." (PMID 37762032, 2023). "Therefore, it is possible that increased miR-200c/141 levels reduce MXRA8 expression which in turn decreases the expression of breast cancer progression genes like ADAMTS1 and BMP2 potentially through increasing histone methylation." (PMID 37762032, 2023). "ADAMTS1 is low expressed in breast carcinoma and plays an inhibitory role in breast cancer." (PMID 34603444, 2021). "Other studies reported also that this drug inhibited both migration and invasion of breast cancer cells through the downregulation of thrombospondin-1 and the upregulation of its degrading protease ADAMTS1 (a disintegrin and metalloprotease with thrombospondin-1 motifs)." (PMID 32519230, 2020). "Through a study of ADAMTS1 in breast cancer, its expression level was found to be low." (PMID 32884571, 2020). "In contrast, in the absence of fibulin-1, ADAMTS-1 shows a protumor function, indicating that the fibulin-1/ADAMTS-1 interaction could be considered a good prognostic factor in mammary tumors." (PMID 31508361, 2019). "TSP-1 is reported to induce an invasive phenotype in various cancer cells, we asked whether GW501516-activated PPARδ induces phenotypic changes, such as invasion, via ADAMTS-1-mediated regulation of TSP-1 in breast cancer cells." (PMID 29212212, 2017). "Furthermore, ligand-activated PPARδ suppressed invasion of breast cancer cells in an ADAMTS1-dependent manner." (PMID 29212212, 2017). "In addition, breast cancer cells induce stromal fibroblasts to secrete ADAMTS1, thereby facilitating cancer cell invasion." (PMID 29212212, 2017). "In addition, pretreatment with GSK0660 significantly inhibited GW501516-induced expression of ADAMTS1 mRNA, confirming involvement of PPARδ in GW501516-mediated upregulation of ADAMTS1 in breast cancer cells." (PMID 29212212, 2017). "Furthermore, GW501516-activated PPARδ suppressed invasion of human breast cancer cells via a mechanism mediated by ADAMTS1." (PMID 29212212, 2017). "ADAMTS1 gene is down-regulated in breast carcinomas with respect to non neoplastic mammary tissue." (PMID 28173833, 2017). "The specific influence of stromal ADAMTS1 has been suggested in some studies of breast cancer, and the use of the ADAMTS1 knockout mice, in combination with a spontaneous model of mammary carcinogenesis, revealed its participation in tumor growth and metastasis." (PMID 27120788, 2016). "ADAMTS1 could bind and degrade extracellular matrix components and plays an important role in triggering pulmonary metastasis of mammary carcinoma." (PMID 26337468, 2015). "Furthermore, a decreased expression of ADAMTS-1 in breast cancer favors breast cancer migration and invasion." (PMID 24457941, 2014). "However, the role of ADAMTS-1 in human breast cancer is not fully understood and requires further investigation." (PMID 23289900, 2013). "In parallel studies for downregulated genes, we were able to identify seven genes with mutations in colon cancer (DPP10, PCSK2, ADAM33, RELN, CAPN13, ADAMTS1 and ADAMTS15), and five genes with mutations in breast carcinomas (MASP3, ABHD12B, TLL1, CPA3 and DPP6)." (PMID 24243807, 2013). "Therefore, this series of experiments suggests that VEGF is involved in the effects mediated by ADAMTS-1 in breast cancer cells." (PMID 23289900, 2013). "In addition, ADAMTS-1 knockdown stimulated migration, invasion and invadopodia formation in breast cancer cells in vitro." (PMID 23289900, 2013). "Finally, we investigated the mechanism by which ADAMTS1 was activated in NAF co-cultured with breast cancer cells." (PMID 22514714, 2012). "Consistently, ADAMTS1 Ab also suppressed NAF 200N.E4.P3-mediated invasion of breast cancer cells." (PMID 22514714, 2012).
breast carcinoma (continued). "Previous study has shown that ADAMTS1 could physically interact with VEGFC in breast cancer cells." (PMID 30131072, 2018). "Co-culture of stromal fibroblasts with breast cancer cells results in elevated expression of SRGN and secretion of ADAMTS1 in fibroblasts and induced invasiveness of tumor cells." (PMID 38672477, 2024). "ADAMTS1 gene is differentially expressed low in various cancer types, including NSCLC, prostate, liver, colorectal, and breast cancers." (PMID 35625488, 2022). "For example, ADAMTS1 expression was decreased in BRCA, which can stimulate the migration and invasion of breast cancer cells in vitro." (PMID 33179733, 2020). "QPCR analysis confirmed the up-regulated expression of MMP1, MMP13, and MMP11 genes and down-regulated expression of ADAMTS1 and ADAMTS5 genes in breast cancers observed in the microarray experiments." (PMID 31292488, 2019). "These interactions can modify the protumor properties exhibited by ADAMTS-1 and ADAMTS-12 in breast cancer cells." (PMID 31508361, 2019). "The present findings show that activation of PPARδ regulates migration and invasion of human breast cancers MDA-MB-231, MDA-MB-435, and ZR-75-1 cells by upregulating ADAMTS1 expression, thereby modulating the level of TSP-1." (PMID 29212212, 2017). "We show that activation of PPARδ by GW501516 inhibits migration and invasion of breast cancer cells, and that PPARδ exerts its inhibitory effects by downregulating TSP-1 expression in a process mediated by transcriptional upregulation of ADAMTS1." (PMID 29212212, 2017). "ADAMTS-1 expression was decreased in human breast tumors, and ADAMTS-1 knockdown stimulated migration, invasion and invadopodia formation in breast cancer cells in vitro." (PMID 23289900, 2013). "MMP-1, ADAMTS1, OPN, and PTHrP were up-regulated in MDA-231BO2 breast cancer cells upon RANKL stimulus." (PMID 23696795, 2013). "On the other hand, breast cancer cells exhibit lower levels of ADAMTS-1 in the extracellular matrix, and in this scenario, VEGF is no longer sequestered and becomes freely available to bind VEGFR, which increases breast cancer cell migration and invasion." (PMID 23289900, 2013). "To further evaluate the role of ADAMTS-1 in tumor biology, we studied the role of this protease in the regulation of migration and invasion in MDA-MB-231 and MCF7 breast cancer cells." (PMID 23289900, 2013). "Together, these results provide a rationale for targeting EGF-like factors (HB-EGF, AREG and TGF-α) and proteases (MMP1 and ADAMTS1) in tumour cells, as well as EGFR in osteoblasts for controlling osteolytic bone metastasis of breast cancer." (PMID 20010942, 2010). "Here, we show that peroxisome proliferator-activated receptor (PPAR) δ regulates migration and invasion of human breast cancer cells via thrombospondin-1 (TSP-1) and its degrading protease, a disintegrin and metalloprotease domains with thrombospondin motifs 1 (ADAMTS1)." (PMID 29212212, 2017). "As immunotherapy using an anti-ADAMTS1 antibody has been reported to be efficient against 4T1-induced tumorigenesis in mice, our study reinforces the idea of therapeutically targeting ADAMTS1 – and other NFAT targets – to prevent breast cancer metastasis." (PMID 25719243, 2015). "ADAMTS-1 expression decreased in human breast tumors in vivo, mainly in triple negative cases (ER-, PR-, and Her-2), and ADAMTS-1 knockdown was shown to stimulate migration, invasion and invadopodia formation in breast cancer cells in vitro." (PMID 23289900, 2013). "Therefore, the loss of MXRA8 may influence intracellular signaling pathways that in turn alter the expression of genes like ADAMTS1, TIE1, and BMP2 that regulate breast cancer metastasis." (PMID 37762032, 2023). "Consequently, the simultaneous presence of fibulin-1 and ADAMTS-1 or of fibulin-2 and ADAMTS-12 could be considered a good prognostic factor in breast cancer." (PMID 31508361, 2019).